CAV1 (caveolin 1)
Diseases named in the same sentence as CAV1 in open-access papers (continued):
Sharing a sentence is not in itself a finding about the gene and the disease.
cancer (664 papers, 2002 to 2026). A tumor composed of atypical neoplastic, often pleomorphic cells that invade other tissues. "In cancer-associated fibroblasts, CAV1 was significantly downregulated accompanied by a significant upregulation of ketogenesis-related genes, reflecting an intrinsic connection between CAV1 and ketone metabolism in fibroblasts." (PMID 40180904, 2025). "Several studies have shown that CAV1 overexpression is associated with cancer progression, angiogenesis, and metastasis." (PMID 40143204, 2025). "Our clinical analysis using scRNA RNA-seq and bulk RNA-seq data showed that CAV1+ cancer cells in HCC tissues are associated with higher recurrence rates." (PMID 40715090, 2025). "In pancreatic cancer, Cav-1 has been associated with heightened glycolysis, contributing to cancer-induced cachexia, a syndrome characterized by severe weight loss and muscle wasting." (PMID 40243482, 2025). "They found that lactate and pyruvate secreted by CAFs through aerobic glycolysis are absorbed and utilized by nearby cancer cells, and verified this mechanism in matrix cells deficient in caveolin-1 (Cav-1)." (PMID 39876898, 2024). "At the molecular level, oxidative stress mediates the activation of HIF-1 and NF-κB in CAFs, further inducing autophagic degradation of Cav-1, and Cav-1-deficient CAFs exhibit protection against apoptosis in cancer cells." (PMID 39680287, 2024). "CAV1, a membrane molecule linked to cancer metastasis, participates in the integrin signaling pathway." (PMID 39494337, 2024). "The association of Ago2 and CAV1 on the plasma membranes increases in cancer cells (i.e., HCC1806, MDA-MB-231, and A549 cells), compared to that of normal epithelial cells." (PMID 38649663, 2024). "To understand the underlying mechanism of different Ago2/CAV1 interactions in cancer cells and normal epithelial cells, we investigated the regulation of Ago2/CAV1 interaction through the charged residues of Ago2." (PMID 38649663, 2024). "The association of Ago2 and CAV1 on plasma membranes was decreased by blocking Ago2/CAV1 interaction with P2 peptides in cancer cells (i.e., HCC1806 and A549 cells)." (PMID 38649663, 2024). "Blocking Ago2/CAV1 interaction with P2 peptides increased the levels of SCAI mRNAs in A549 cancer cells, which are inversely associated with the levels of miR-3613-3p." (PMID 38649663, 2024). "CAV1 is more highly expressed in advanced cancer than benign tissues and is associated with poor prognosis." (PMID 39494337, 2024). "Previous studies have implicated Cav-1 and lipid rafts in cancer metastasis by promoting cellular behaviors involved in metastatic cascades." (PMID 39244591, 2024). "TGFβ, however, by increasing IL-6 and MCT4, as well as down-regulating Cav1, is known as the most important cytokine contributing to carcinoma-associated fibroblast differentiation." (PMID 38361760, 2024). "Earlier studies indicated that the loss of stromal CAV1, which can be induced by ROS emitted from cancer cells, eventually results in stromal CAV1 loss." (PMID 38067169, 2023). "CAV1 has also been linked to radioresistance in various cancers through regulation of tyrosine kinase receptor membrane trafficking and thereby activating DNA repair mechanisms." (PMID 37017811, 2023). "There are some studies of caveolin expression in human prostate tissue showing association of caveolin-1 with cancer progression and recurrence." (PMID 36869937, 2023). "Cav-1 is not only an intracellular protein that regulates cell function but also present in extracellular space and closely associated with cancer cell metastasis." (PMID 37056561, 2023). "In breast cancer, ROS production by cancer cells induces loss of Cav-1 in stromal cells, allowing CAFs to accumulate ROS and activate HIF-1α, consequently reprogramming CAFs and inducing autophagy." (PMID 37033960, 2023). "Accordingly, low levels of stromal Cav-1 are associated with poor prognosis in various cancers, including breast, prostate, and colorectal cancer." (PMID 38067169, 2023).
cancer (continued). "Cav1-deficient cancer-associated fibroblasts (CAFs) show decreased contractility because Cav1 favors cell elongation in 3D cultures and promotes Rho-dependent contraction through the regulation of p190RhoGAP." (PMID 36980283, 2023). "How Cav-1 expression affects junctional integrity and promotes contact inhibition in association with cadherins or catenins remains poorly characterized in cancer cells." (PMID 35954304, 2022). "Recently, a study in cancer cell lines linked micro-RNAs (miR)-mediated regulation of CAV1 to drug resistance." (PMID 35158857, 2022). "The expression of the CAV1 gene is associated with many human diseases, including pulmonary hypertension, hypertriglyceridemia, and cancer." (PMID 36233075, 2022). "The loss of Cav1 is sufficient to confer a cancer-associated fibroblast (CAF) phenotype with a change in gene-expression profile, altered deposition of extracellular-matrix components, thickening of the interstitial space, and fibrosis." (PMID 35158857, 2022). "Known as a protein that associates with cell surface caveolae, caveolin-1 (CAV1) plays roles in multiple cancer-associated processes e.g., cell migration and metastasis." (PMID 36230825, 2022). "Caveolin-1 plays an important role in cancer genesis because it is overexpressed or mutated in many solid human tumors." (PMID 35064107, 2022). "Yet, gain-of-function mutations of CAV1 are rare—in TCGA cancers there are infrequent (0.3%) CAV1 missense mutations scattered throughout the gene." (PMID 35158857, 2022). "Caveolin-1 is an important signaling protein that has been associated with several cancers, and its overexpression is associated with cancer progression and resistance to therapies." (PMID 36299636, 2022). "The increase in CAV1 is, in most cancers studied so far, associated with phenotypes ascribed to advanced stages such as increased proliferation rates, invasion, metastasis and treatment resistance." (PMID 35158857, 2022). "There is also evidence of the effect of oxidative stress in CAFs, characterised by the loss of caveolin-1 (Cav-1) caused by the cancer cells, on inducing genomic instability in adjacent cells through a bystander effect." (PMID 36101394, 2022). "Recently, many studies have demonstrated that CAVs, especially CAV1, are abnormally expressed in a variety of tumors and implicated in tumorigenesis and cancer progression." (PMID 36147736, 2022). "CAV1 and caveolae have been implicated in cancer cell metabolic regulation, including mitochondrial bioenergetics and fatty acid metabolism." (PMID 35660849, 2022). "Cav-1 downregulation was observed in cancer-associated fibroblasts (CAFs), obtained as result of a coculture of normal fibroblasts and MCF-7 cells." (PMID 36619302, 2022). "Taken together, our study not only provided a supporting evidence for the anti-metastasis activities of CP against HBV-associated HCC, but it also addressed the novel role of Cav-1 in mediating the Akt/GSK3β/β-catenin axis during advanced cancer stages." (PMID 34168559, 2021). "Studies have suggested the role of Cav-1 in the integrin-mediated ECM remodeling of cancer-associated fibroblasts (CAFs), and in integrin-dependent invasion and cancer metastasis." (PMID 33920031, 2021). "Further, gene amplification of CAV1 by copy number variation has been linked to cancer aggression and metastasis." (PMID 34762666, 2021). "Among them, CAV-1 was regarded as one of core functional cancer-associated genes of HBV-associated HCC." (PMID 34168559, 2021). "Cav-1 is a constituent protein of plasma membrane and has been reported to be closely implicated in cancer tumorigenesis and metabolism modulation." (PMID 34568078, 2021). "Taken together, these results support a novel pan‐cancer mechanism for CAV1‐driven exosomal release of hnRNPK and associated miRNA in metastasis, which is modulated by the membrane lipid environment." (PMID 33931969, 2021).
cancer (continued). "Caveolin-1 (Cav-1) is a scaffolding protein which is involved in several cancer-associated processes as important component of the caveolae." (PMID 33774714, 2021). "Cav-1 phosphorylation has been associated with cellular processes such as focal adhesion dynamics, cell migration and invasion, cancer cell metabolism, and response to mechanical, oxidative stress." (PMID 34790658, 2021). "caveolin-1 is a 21 kDa membrane protein enriched in caveolae and functionally associated with endocytosis, extracellular matrix organization, cell migration, cancer signaling and radio-resistance in other malignancies." (PMID 34762666, 2021). "Cav-1 was previously shown to control the cellular level of integrins β1, α2, and α5, which are associated with the increased motility and invasion of cancer cells." (PMID 33920031, 2021). "For some tumors, caveolin-1 overexpression is associated with protumoral mechanisms; in contrast, for other cancer types, the loss of caveolin-1 expression is associated with poor prognosis." (PMID 33037799, 2021). "Previously, there have been similar studies on the associations between Cav-1 and β-catenin during cancer initiation and progression." (PMID 34168559, 2021). "Depletion of CAV1 and the resultant reduction in the number of caveolae have been recently associated with a broad range of disease states such as cancer and cardiovascular and pulmonary diseases." (PMID 32082483, 2020). "Particularly, Cav-1 is found to be associated with cell differentiation, proliferation, migration and invasion in cancers." (PMID 31991790, 2020). "We observed that CAV1 presence in cancer cells was associated with diminished HIF1α activity rather than protein levels and linked this to reduced nitrosylation in the presence of CAV1." (PMID 32825247, 2020). "For this reason, CAV1 dysfunction is associated with different type of human diseases including lipodystrophy, muscular dystrophies, pulmonary diseases and cancers, as demonstrated by numerous studies." (PMID 32825330, 2020). "In the stromal cells, absence or loss of stromal CAV1 immunostaining is a novel indicator of poor prognosis in various human cancers, such as breast, gastric and prostate carcinomas, as well as in metastatic melanoma." (PMID 32401768, 2020). "Among the many molecular mechanisms that contribute to metastasis, our group and others have shown that increased expression of the scaffolding protein caveolin-1 (CAV1) is associated with cancer progression." (PMID 31484460, 2019). "Our results suggest that Cav1 Y14 phosphorylation levels play a role in the conflicting demands on metabolic resources associated with cancer cell proliferation versus motility." (PMID 31803361, 2019). "This recruitment is related to cancer cell k-ras expression, hydrogen peroxide excretion, loss of caveolin-1 and induction of CAF oxidative stress, HIF-1α, NF-κB and autophagy." (PMID 31198853, 2019). "Cav-1 can lose its function in cancer repression following inactivation through gene mutation or promoter methylation." (PMID 31759347, 2019). "This review summarized some mechanisms of Cav-1 in cancer progression to profoundly reveal the association between Cav-1 expression and gynecological tumors." (PMID 31759347, 2019). "Pathway analysis of the differentially expressed genes showed that CAV1 knockdown caused overall upregulation of metabolic processes and the downregulation of cancer-related pathways." (PMID 32082178, 2019). "In summary, evidence is available implicating CAV1 as a protein that precludes as well as favors the acquisition of cancer cell traits associated with enhanced or reduced metastatic potential." (PMID 31362353, 2019). "By regulating the Rho inhibitor p190RhoGAP, Cav1 expression results in cancer-associated fibroblasts (CAFs) that promote extracellular matrix (ECM) alignment and stiffening." (PMID 31845647, 2019).
cancer (continued). "Caveolae-associated protein caveolin-1 (Cav-1) plays key roles in cellular processes such as mechanosensing, receptor coupling to signaling pathways, cell growth, apoptosis, and cancer." (PMID 31635212, 2019). "HCC cell lines also show dissimilar expression levels of many known cancer-associated proteins such as caveolin-1 (CAV1), alpha fetoprotein (AFP), and WNT signaling molecules." (PMID 30176945, 2018). "Loss of Cav-1 in CAFs results in additional ROS production in cancer cells, thus forming a positive feedback for the oxidative stress on CAFs and consequently active mitochondrial respiration in cancer." (PMID 29534029, 2018). "The miRNA located within the most commonly effected chromosomal region in SMZL, 7q and the miRNA that target CAV1, a gene implicated in many cancers and located at 7q31, were also a focus of this review." (PMID 30042829, 2018). "The level of expressed CAV1 in cancer-associated stroma has been shown to be associated with clinical parameters such as survival time." (PMID 29850392, 2018). "CAV1 has been found to be involved in a variety of cancer-associated biological processes, including cell migration and metastasis, cell transformation, angiogenesis, multidrug resistance." (PMID 29190968, 2017). "Studies in other cancer types further implicated Cav1 as a pro-survival factor mediating resistance e.g. in pancreatic and lymphoblastoid cancer cells to the cytotoxic action of ionizing radiation (IR) in vitro." (PMID 28112237, 2017). "Cav1 gene expression has been observed to coordinate with Lgals3 in several cancers, and their encoded proteins together have been seen to regulate the downstream pathway signaling." (PMID 29084770, 2017). "Caveolin-1 is known to be expressed in cancer-associated fibroblasts, myoepithelial cells underlying the luminal epithelial cells, endothelial cells, and adipocytes, which clearly correlates with our detection." (PMID 28531107, 2017). "In turn, loss of Cav-1 causes more production of ROS in cancer cells, which initiates the cascade of oxidative stress in CAFs through a positive feedback mechanism." (PMID 28915713, 2017). "The data presented herein clearly show that cordycepin is involved in the JNK/Foxo3a signaling pathway by stimulating CAV1 signaling, and that the consequent activation of Bax/caspase-3-mediated pathway causes cancer cell death." (PMID 28099944, 2017). "Multiple cancer-associated processes are regulated by Cav-1, including cellular transformation, cell death and survival, multidrug resistance, and cell-mediated migration and metastasis." (PMID 29221162, 2017). "Recently, increasing evidences have showed that the oxidative stress processes in cancer cells were closely associated with Cav-1." (PMID 28546853, 2017). "Kaplan-Meier survival curve revealed a significant association between high expression of tumoral Cav-1 protein in metastatic lymph node and cancer-specific death (P = 0.004)." (PMID 28828003, 2017). "The association of CAIX with caveolin-1 was partially attenuated by acidosis, i.e. another important feature of malignant tumors." (PMID 28978009, 2017). "On the other hand, a low CAV1 expression in cancer-associated fibroblasts (CAFs) is induced by oxidative stress that accounts for CAV1 degradation through autophagy, and the loss of CAV1 expression enhances oxidative stress and autophagy in a feedforward loop." (PMID 29099748, 2017). "Recently, numerous literatures have reported that Cav-1 regulated multiple cancer-associated cellular processes, and its expression is a marker that predicts poor cancer patient prognosis." (PMID 26919102, 2016). "Increase in the level of FASN and Cav-1 has been reported to be associated with development of resistance to cancer therapy." (PMID 27980732, 2016). "Tyrosine phosphorylation on tyrosine 14 of Cav-1 (pY14 Cav-1) is a typical activation of Cav-1, which is crucial for regulation of multiple cancer-associated cellular processes." (PMID 26919102, 2016).
cancer (continued). "Lisanti and colleagues have shown that downregulation of caveolin-1 expression in cancer-associated fibroblasts leads to increased expression of glycolysis regulators and glycolytic enzymes therefore creating a lactate- and pyruvate-rich microenvironment." (PMID 27705926, 2016). "The loss of Caveolin 1 (CAV1), which is triggered upon initiation of oxidative stress from adjacent cancer cells and implemented by means of autophagolysosomal degradation, appears to play a major role in the onset of the myofibroblast phenotype." (PMID 27590516, 2016). "Accordingly, cancer associated fibroblasts cultured in high glutamine media had suppressed CAV1 expression and increased autophagy." (PMID 27852311, 2016). "Elongated Cav-1 positive but Desmin negative cells (non muscle cells) were however observed and such areas were generally SMA positive suggesting that some myofibroblasts (cancer associated fibroblasts, CAFs) express Cav-1." (PMID 27764093, 2016). "Cav-1 is a mediator of vesicular transport, cholesterol homeostasis and signal transduction, and has been implicated in cancer." (PMID 26919102, 2016). "Taken together, these studies reveal that CAV1 is associated with fatty acid metabolism, offering insights for onward investigation in cancer." (PMID 27852311, 2016). "ROS produced by cancer cells induce loss of Cav-1 in stromal cells, driving glycolysis switch and lactate excretion." (PMID 27595103, 2016). "Both CaV1 and CaV3 channels have been implicated in the proliferative pathophysiology of various cancers, and their contributions are reviewed below." (PMID 26010603, 2015). "Alternatively, CAV1 is upregulated in some metastatic and multidrug resistant cancer cells where expression is associated with cell survival and proliferation." (PMID 26054531, 2015). "Studies in other cancer types have implicated Cav1 as a pro-survival factor mediating resistance of pancreatic and lymphoblastoid cancer cells to the cytotoxic action of ionizing radiation in vitro." (PMID 25985209, 2015). "Firstly, several epidemiological studies have revealed a correlation between the Cav-1 gene and the risk of several types of cancer." (PMID 25202343, 2014). "Previous studies of caveolin-1 cancer-associated fibroblasts also revealed a metabolic switch from an oxidative mitochondrial phenotype to a glycolytic phenotype." (PMID 24498385, 2014). "The stromal cell that shows increased autophagy activity is called the cancer-associated fibroblast according to the reverse Warburg effect theory, and it is characterized by caveolin-1 loss." (PMID 25140630, 2014). "CAV1 is the main component of caveolae membrane structures, and has been implicated in diverse human cancers." (PMID 25180681, 2014). "Cav-1 expression in cancer-associated fibroblasts was lower than that in paracancer-associated and in normal fibroblasts." (PMID 24949874, 2014). "The initiation and progression of cancer by cav-1 is linked to its tendency to form platforms that aggregate membrane proteins for cell proliferation signaling." (PMID 23934233, 2013). "Decreased expression of caveolin-1 is associated with a poorer prognosis of breast and other cancers." (PMID 23006971, 2012). "It is well known that Cav-1 regulates multiple cancer-associated processes in cancer cells, including cell proliferation, migration and metastasis, cell death and survival, and multidrug resistance." (PMID 23203033, 2012). "On the other hand, up-regulation of Cav-1 has been observed in highly metastatic human cancers, and is associated with poor clinical prognosis and with resistance to therapy." (PMID 20700465, 2010).